RNU4-17P (RNA, U4 small nuclear 17, pseudogene)
Gene: Small nuclear RNA gene on chromosome 18 (60,163,567 to 60,163,707, forward strand). Ensembl gene ENSG00000202468.
Homologues: Orthologues: chimpanzee U4 (98% identical), macaque U4 (95% identical), dog U4 (62% identical), guinea pig U4 (57% identical), dog U4 (46% identical). Paralogues in human: RNU4-10P (79% identical), RNU4-49P (76% identical), RNU4-32P (74% identical), RNU4-84P (74% identical), RNU4-81P (73% identical), RNU4-50P (72% identical), RNU4-75P (71% identical), RNU4-15P (69% identical), RNU4-70P (69% identical), RNU4-83P (69% identical), RNU4-52P (68% identical), RNU4-90P (68% identical), and 82 more.